TAFA2 (TAFA chemokine like family member 2)
Description:
Has a role as neurotrophic factor involved in neuronal survival and neurobiological functions.
Synonyms: FAM19A2; TAFA-2
Tractability: Antibody: UniProt predicts a signal peptide or a membrane-spanning region.
Gene: Protein-coding gene on chromosome 12 (61,707,341 to 62,279,150, reverse strand). Ensembl gene ENSG00000198673.
Subcellular location: Cytoplasm; Nucleus
Gene Ontology:
Molecular function: receptor ligand activity
Biological process: memory; visual learning; signal transduction
Cellular component: cytoplasm; nucleus
Genetic constraint (gnomAD): Loss-of-function variants: 6 observed, 14.39 expected, observed/expected ratio (o/e) 0.42, 90% interval 0.23 to 0.82. The upper end of that interval is the gene's LOEUF score, 0.82, which puts it in group 3 of 6, group 1 being the genes least tolerant of losing a copy. Missense variants: 74 observed, 123.18 expected, observed/expected ratio (o/e) 0.6, 90% interval 0.5 to 0.73. Synonymous variants: 50 observed, 43.74 expected, observed/expected ratio (o/e) 1.14, 90% interval 0.91 to 1.45.
Homologues: Orthologues: chimpanzee TAFA2 (100% identical), dog TAFA2 (100% identical), rabbit TAFA2 (100% identical), pig TAFA2 (99% identical), macaque TAFA2 (98% identical), mouse Tafa2 (97% identical), rat Tafa2 (97% identical), tropical clawed frog tafa2 (86% identical), guinea pig TAFA2 (66% identical). Paralogues in human: TAFA4 (65% identical), TAFA3 (63% identical), TAFA1 (56% identical).
Diseases named in the same sentence as TAFA2 in open-access papers:
TAFA2 is named in the same sentence as 11 diseases in open-access papers, as found by Europe PMC text mining. Sharing a sentence is not in itself a finding about the gene and the disease. The quoted sentences say what the papers report.
Anxiety (1 paper, 2024). Intense feelings of nervousness, tension, or panic often arise in response to interpersonal stresses. "TAFA chemokine like family member 2 (Tafa2) is associated with learning and memory as well as anxiety-like behavior in mice." (PMID 38861567, 2024).
epidermolysis bullosa (1 paper, 2021). Epidermolysis bullosa (EB) is a group of genetic skin diseases that cause the skin to blister very easily. "The partial deletion of LAMA3 is responsible for epidermolysis bullosa in horses; NAALADL2 is believed to be responsible for immune homeostasis, and TAFA2 (FAM19A2) is believed to be responsible for the regulation of feed intake and metabolic activities in mice." (PMID 34051743, 2021).
pancreatic cancer (1 paper, 2025). "The results showed that TAFA2 and POSTN were significantly elevated in IR-resistant pancreatic cancer cells, suggesting that TAFA2 may play an important role in radiotherapy resistance of pancreatic cancer." (PMID 40103813, 2025).
TAFA2 also shares sentences with these, for which no sentence is quoted: tumor (2 papers); autism (1); chronic obstructive pulmonary disease (1); glioma (1); heart diseases (1); neurological diseases (1); schizophrenia (1); systemic lupus erythematosus (1).